MITF (melanocyte inducing transcription factor)
Diseases named in the same sentence as MITF in open-access papers (continued):
Sharing a sentence is not in itself a finding about the gene and the disease.
deafness (continued). "It has the function of maintaining the survival and differentiation of cochlear precursor cells, suggesting that there may be other pathways regulating the development of the inner ear in addition to the MITF pathway and in the mechanism of deafness caused by SOX10 mutation." (PMID 33597923, 2020). "Disruptive mutations in MITF also cause Tietz syndrome, which is characterized by depigmentation of the skin, hair, iris and severe hearing loss, and Waardenburg syndrome type 2A, which is characterized by patchy depigmentation of the skin and bi- or unilateral deafness in humans and mice." (PMID 31703548, 2019). "However, low levels of bilateral deafness among animals with the low-risk haplotype suggest that while the extreme white encoded by the SINE element may partly affect deafness risk, the risk is modified by additional variants in the MITF region in a complex manner." (PMID 36104420, 2022). "MITF deficiency is responsible for COMMAD (coloboma, osteopetrosis, microphthalmia, macrocephaly, albinism, and deafness) syndrome in two unrelated patients, suggesting a role for MITF in regulating various processes beside bone development and homeostasis." (PMID 30837952, 2019). "Across species, the genes identified with deafness or white pigmentation patterns include MITF, PMEL, KIT, EDNRB, CDH23, TYR, and TRPM1 in dog, cat, horse, cow, pig, sheep, ferret, mink, camelid, and rabbit." (PMID 26664958, 2015). "While attempts to identify causative risk variants associated with CSD have been numerous, no genome-wide association study has positively identified MITF as a risk locus for either bilateral or unilateral deafness in the Dalmatian breed to date." (PMID 36104420, 2022). "It is worth noting that patient 3312176 had profound bilateral deafness and freckles caused by NM_198159.3 (MITF): c.1212G>A, but there was no other clinical phenotype associated with WS." (PMID 36568381, 2022). "Since MITF is pivotal in melanogenesis, its heterozygous mutations caused pigmentary diseases such as Waardenburg syndrome IIA7 to demonstrate severe symptoms of deafness or hyperpigmentation." (PMID 36613979, 2022). "The closest recognized gene associated with deafness was SOX10, which is mutated in human Waardenburg Syndrome type IVc and plays a role in regulating MITF, but sequencing in six hearing, two unilaterally deaf, and two bilaterally deaf dogs did not reveal any disease-associated mutations in SOX10." (PMID 32413090, 2020). "The molecular basis of deafness was found in 44.4% (20/45) of the cases with symmetric SNHL, whereas only 1 of 5 cases with asymmetric SNHL was genetically diagnosed (Waardenburg syndrome caused by a MITF mutation)." (PMID 29986705, 2018). "Phenotypes caused by the genes endothelin 3 (END3), endothelin receptor B (EDNRB), microphthalmia-associated transcription factor (MITF), paired box 3(PAX3), SRY-box 10 (SOX10), and snail homolog 2 (SNAI2) can result in decreased melanocytes, white coat color, and ultimately deafness." (PMID 27698666, 2016). "MITF was first identified in the mouse as a locus whose mutation results in the absence of pigment cells causing white coat color and deafness due to melanocyte deficiency in the inner ear." (PMID 19828018, 2009). "In humans, MITF mutations are reported to be associated with Waardenburg syndrome; Tietz albinism deafness syndrome (TADS); coloboma, osteopetrosis, microphthalmia, macrocephaly, albinism, and deafness (COMMAD); non-syndromic hearing loss; and melanoma and renal carcinoma." (PMID 37510362, 2023). "Finally, compound-heterozygous MiTF mutations have been identified in the severe multisystemic disorder termed COMMAD (coloboma, osteopetrosis, microphthalmia, macrocephaly, albinism, and deafness)." (PMID 33441180, 2021). "Biallelic MITF mutations may lead to the recently recognized COMMAD syndrome, which is characterized by the combination of coloboma, osteopetrosis, microphthalmia, macrocephaly, albinism and deafness." (PMID 30651300, 2019).
deafness (continued). "Based on the varying degrees of audiologic phenotypes of MITF-related WS2, including single side deafness, bilateral profound SNHL of SH107-225 may have resulted from the additive effect of single heterozygous c.235delC of GJB2, and the MITF mutation through digenic inheritance." (PMID 27057829, 2016). "In mice, mutant MITF can lead to deafness, bone hyperdensity, small eyes, and absence of pigment in eyes and skin." (PMID 33506017, 2021). "Our results showed that mutations in SOX10 and MITF are two major causes for deafness associated with WS, and de novo mutations were frequently found in probands with SOX10 mutations (3/4) but not in those with MITF mutations (0/2)." (PMID 31960627, 2020). "Our results showed that mutations in SOX10 and MITF are two major causes of deafness associated with WS, and de novo mutations were frequently found in probands with SOX10 mutations but not in those with MITF mutations." (PMID 31960627, 2020). "No significant loci were located within or near the genes MITF, SILV, SOX10, or KITLG, shown in other studies to be associated with deafness." (PMID 26664958, 2015). "Although the piebald locus is caused by MITF and the merle locus is caused by PMEL in dogs, and the white spotting locus is caused by KIT in cats, the genes responsible for the pigment-associated deafness in these species have not yet been identified." (PMID 26664958, 2015).
Waardenburg syndrome (40 papers, 2012 to 2025). A disorder characterized by varying degrees of deafness and minor defects in structures arising from neural crest, including pigmentation anomalies of eyes, hair, and skin. "Waardenburg syndrome (WS), also known as auditory-pigmentary syndrome, is associated with various genes, such as MITF, PAX3, SNAI2, SOX10, EDNRB, and EDN31." (PMID 40745198, 2025). "The MITF protein is susceptible to mutations that impair dimer formation, particularly in cases of MITF loss-of-function mutations, as found in human Waardenburg syndrome type 2A." (PMID 38534309, 2024). "Here, the authors reveal that MITF has a very long chromatin-bound half-life, and that MITF target selectivity is regulated by K206 acetylation, a residue linked to Waardenburg syndrome." (PMID 37770430, 2023). "The results reveal an acetylation-mediated switch that suppresses differentiation and provides a mechanistic explanation of why a human K206Q MITF mutation is associated with Waardenburg syndrome." (PMID 37770430, 2023). "In proband 38 and 43, a missense variant (c.641G>A) and a nonsense variant (c.877C>T) and in MITF were identified by exome sequencing, respectively, which led to the genetic diagnosis of Waardenburg syndrome, type 2A (OMIM# 193510)." (PMID 35761346, 2022). "Four had Waardenburg syndrome (WS)-II type A and type E, caused by MITF and SOX10 gene variants, respectively." (PMID 36568381, 2022). "Here, clinical manifestations and mutation detection of the MITF gene are reported in a sizable family in Iran with Waardenburg syndrome type 2A." (PMID 34544414, 2021). "The woman had non-syndromic profound SNHI caused by bi-allelic MYO15A variants and the man had Waardenburg syndrome caused by a dominant MITF variant." (PMID 34943631, 2021). "Heterozygous MITF mutations cause Waardenburg syndrome, type 2A (WS2A) and Tietz (or Tietz albinism-deafness) syndrome, with autosomal dominant inheritance." (PMID 32728090, 2020). "One novel variant in the USH2A gene was detected in one individual, and one novel and one known variant were also detected in the PAX3 and MITF genes, respectively, in two persons with Waardenburg syndrome and profound HL." (PMID 31850270, 2019). "Mutations in either of two genes, PAX3 or SOX10 (OMIM entries 606597 and 602229, respectively), in humans result in Waardenburg syndrome and a reduction in melanocytes, similar to mutations in MITF, and mice mutant in either gene also lack melanocytes." (PMID 25670789, 2015). "Additionally, Patient 34, a 17-month-old boy whose HL was the only feature detected during the initial clinical evaluation, presents a known heterozygous de novo pathogenetic variant in the MITF gene, causative of Waardenburg syndrome type 2a (MIM: # 193510)." (PMID 36979683, 2023). "We found the variants responsible for the disease in one patient diagnosed with Waardenburg syndrome, presenting the variant responsible for the disease in MITF, and one patient diagnosed with BOR syndrome was found to present with the pathogenic variant in EYA1." (PMID 33297549, 2020). "MITF is a known gene underlying autosomal dominant hearing loss, Waardenburg syndrome (WS)." (PMID 32728090, 2020). "Deficiency of MITF may result in hypopigmentary disorders and vitiligo as well as more severe disease phenotypes such as Waardenburg syndrome, a disease associated with MITF mutation." (PMID 32226536, 2020). "Genetic studies suggest that Waardenburg syndrome is caused by mutations of PAX3 and other genes such as MITF, SOX10, EDN3, EDNRB and SNAI21,9,13,35–37." (PMID 38278860, 2024). "Perturbations to MITF are responsible for several audio-visual disorders across taxa, including Waardenburg syndrome and Tietzs syndrome in humans." (PMID 38092373, 2024). "This family was already considered to be solved, due to an inherited likely pathogenic c.662A>G (p.Asn221Ser) (GenBank: NM_000248.4) variant in MITF (MIM: 156845), a gene associated with Waardenburg syndrome, type 2A (MIM: 193510)." (PMID 38776926, 2024).
Waardenburg syndrome (continued). "Waardenburg syndrome is susceptible to being misdiagnosed as autosomal recessive due to PAX3 spontaneous mutation and ignores MITF-related freckle phenotype." (PMID 36504663, 2022). "In humans, as for some mutations in MITF, protein-changing variants in PAX3 have been shown to cause a similar form of Waardenburg syndrome, which is characterized by wide set eyes, hearing loss and regions of depigmentation in the iris, hair and skin." (PMID 31703548, 2019). "Waardenburg syndrome type 2A (OMIM193510), caused by pathogenic variants in the MITF gene, can also present as non-syndromic SNHL or as sHL with heterochromia iridum being the most common secondary feature." (PMID 29293505, 2018). "Six genes involved in Waardenburg syndrome include PAX3 (encoding the paired box 3 transcription factor), MITF (microphthalmia-associated transcription factor), EDN3 (endothelin 3), EDNRB (endothelin receptor type B), SOX10 (encoding the Sry bOX10 transcription factor), and SNAI2 (snail homolog 2)." (PMID 35790984, 2022). "Mutations of different genes like MITF (microphthalmia-associated transcription factor), PAX3 (Paired Box Gene 3), SOX10, and EDNRB (endothelin receptor type B, gene) have been noted in causing mild or incomplete phenotypic expression of symptoms in Waardenburg syndrome." (PMID 31998473, 2020). "Although the Waardenburg syndrome genes PAX3, SOX10, MITF, EDN3 and EDNRB were not dramatically affected at the mRNA level, expression of the piebaldism gene KIT was significantly down-regulated upon loss of YY1." (PMID 22570637, 2012).
renal cell carcinoma (36 papers, 2012 to 2026). "Xp11 translocation renal cell carcinoma (RCC), a member of the microphthalmia-associated transcription factor (MiTF) family, is a rare renal tumor characterized by different translocations involving the TFE3 gene." (PMID 31828108, 2019). "This category of RCC includes renal oncoytoma (RO), the eosinophilic variant of chromophobe renal cell carcinoma (Chr-RCC), and some less common entities like succinate dehydrogenase (SDH)-deficient RCC, MiTF translocation RCC (especially TFEB), and epithelioid angiomyolipoma (AML)." (PMID 38892169, 2024). "MiTF/TFE translocation renal cell carcinomas represent up to 40% of all pediatric and adolescent RCCs and 1–4% of adult RCCs." (PMID 35886994, 2022). "MiTF/TFE translocation renal cell carcinoma (tRCC) is a rare and aggressive subtype of RCC representing the most prevalent RCC in the pediatric population (up to 40%) and making up 4% of all RCCs in adults." (PMID 35886994, 2022). "TFEB or TFE3 fusion with other partner genes may be the initiating factors for MITF translocation renal cell carcinoma." (PMID 36550835, 2022). "Microphthalmia Transcription Factor (MITF)family translocation renal cell carcinoma (tRCC) is a rare RCC subtype harboring TFE3/TFEB translocations." (PMID 30591082, 2018). "Microphthalmia Transcription Factor (MiTF) family translocation renal cell carcinoma (tRCC) is a subtype of RCC characterized by chromosomal translocations involving TFE3 and TFEB transcription factor genes." (PMID 30591082, 2018). "MiT family translocation renal cell carcinoma (tRCC) is a sporadic RCC characterized by fusion genes involving the MiT/TFE family genes, MITF, TFEB, and TFE3 and defined as an MiT family translocation RCC in the 2016 WHO classification." (PMID 36672892, 2023). "Translocation renal cell carcinomas (T-RCCs) are driven by somatic translocation involving a member of microphtalmia (MiT) transcription factor family genes on chromosome X (i.e., TFE3, TFEB or MITF) with other partner genes." (PMID 36902045, 2023). "A rare subtype of RCC, translocation renal cell carcinoma (tRCC), which occurs in patients before 40 years, harbors specific translocations of TFE3, TFEB and MITF leading to their overexpression." (PMID 33276788, 2020).
microphthalmia (34 papers, 2012 to 2025). Congenital or developmental anomaly in which the eyeballs are abnormally small. "Transcriptional regulation occurs through Microphthalmia-associated transcription factors (MiTF/TFE), which bind directly to the CLEAR site located in the third intron of the FAM134B gene, thereby promoting FAM134B expression." (PMID 41198618, 2025). "Translocation RCC, or microphthalmia-associated transcription factor family translocation RCC (MiTF-tRCC), encompasses a rare group of diseases involving translocations affecting the short arm of the X chromosomes and fusions of the TFE3, TFEB, or MITF genes." (PMID 40361453, 2025). "The TFE3 gene, located on chromosome Xp11.23, encodes a transcription factor belonging to the Microphthalmia transcription family (MiTF), also including MiTF, TFEB, and TFEC." (PMID 39410016, 2024). "MITF deficiency is responsible for theCOMMAD syndrome (Coloboma, Osteopetrosis, Microphthalmia,Macrocephaly, Albinism, and Deafness)." (PMID 37465191, 2023). "The Microphthalmia family of bHLH-LZ transcription factors (MiT/TFE) consists of four members: microphthalmia-associated transcription factor (MITF), TFEB, TFE3, and TFEC." (PMID 37123908, 2023). "Specifically, CDON and MITF are associated with eye size, deleterious mutations of which have been correlated with microphthalmia." (PMID 36192687, 2022). "Members of the Microphthalmia-associated transcription factor family (MiT), including MITF, TFE3 and TFEB, play a central role in regulating cellular homeostasis in response to metabolic pressure and are considered master regulators of lysosomal biogenesis." (PMID 35842725, 2022). "MITF is a microphthalmia-associated transcription factor and its germline mutations are associated with clinically distinct disorders." (PMID 36212129, 2022). "The Microphthalmia-associated transcription factor family includes the basic helix-loop-helix domain-containing transcription factors MITF, TFE3, TFEB, and TFEC." (PMID 35842725, 2022). "In melanocytes, cAMP’s corresponding elements bind to the Creb protein to autophosphorylation and activate MITF (Microphthalmia-associated transcription factor)." (PMID 34014984, 2021). "Here we demonstrate that the Microphthalmia-associated transcription factor (MITF) directly controls general transcription and UVR-induced nucleotide excision repair by transactivation of GTF2H1 as a core element of TFIIH." (PMID 30651597, 2019). "We detected a de novo Microphthalmia-associated transcription factor (MITF) (NM_000248) variant, p.R341C, in one of the c.235delC carriers (SH107-225)." (PMID 27057829, 2016). "Microphthalmia-associated transcription factor (MITF) gene mutations account for about 15% of WS type II (WS2) cases." (PMID 24194866, 2013). "Among those, for the loci microphthalmia-associated transcription factor (MITF, microphthalmia), c-KIT (Dominant White Spotting) and SCF (Steel), it is possible to obtain completely white live animals." (PMID 22719917, 2012). "Similarly, abolishing SUMO conjugation upregulates expression of MITF (Microphthalmia-associated transcription factor) MITF by enhancing SOX10 interaction with the cofactor paired box 3 (PAX3)." (PMID 34356679, 2021). "Among them, Microphthalmia-associated transcription factor (MITF) is the most common." (PMID 32547879, 2020). "Complex heterozygous mutations in the MITF genehave most recently been found in two unrelated patientswith COMMAD syndrome manifesting coloboma, osteopetrosis,microphthalmia, macrocephaly, albinism anddeafness." (PMID 37465191, 2023). "Mitf-mutated mice show a plethora of pleiotropic phenotypes, such as microphthalmia, deafness, abnormal pigmentation, retinal degeneration, reduced mast cell numbers and osteopetrosis, revealing a greater requirement for MiTF activity in cells and tissue." (PMID 33441180, 2021).
microphthalmia (continued). "MITF (Microphthalmia transcription factor) is a helix-loop-helix (HLH) domain containing factor with a basic and leucine zipper domain essential for mast cell development as evident by severely reduced mast cell numbers in MITF mutant mice." (PMID 35387064, 2021). "So, while there are clear changes in the OB due to the mutation, the authors state that there are other effects (e.g., microphthalmia), so the change in behaviour may result from other effects of MITF in other neuronal systems just as well." (PMID 32193365, 2020). "We identified motifs associated with the EGR family of TFs in EC1 (late responsive IL-4 clusters) and the Microphthalmia-associated (MAF) TF family in EC2 and EC3 (early and intermediate responsive IL-4 clusters), as proposed by recent studies, as well as MITF and RUNX under the IL-4 specific ECs." (PMID 30799488, 2019). "Similar to what has been observed in zebrafish, mutations in OTX2 but not MITF have been identified in cases of severe human RPE developmental abnormalities such as microphthalmia and anophthalmia." (PMID 23139843, 2012). "However, it is also possible that the upregulation of MITF observed in microphthalmia patient OVs may promote ECM production due to an imbalance between the presumptive NR and RPE." (PMID 38821055, 2024). "Regarding the central role of MITF in melanocyte lineage development, the ocular structure of CRTC3-null mice was comparable to the control mice with respect to microphthalmia or decoloration." (PMID 34815795, 2021). "MITF expression is upregulated in both datasets, further strengthening the notion that the acquisition of a more RPE-like rather than NR cell fate is a common abnormality in microphthalmia patients and multiple genes may act in this pathway." (PMID 38821055, 2024).